BMAL1 (basic helix-loop-helix ARNT like 1)
Diseases named in the same sentence as BMAL1 in open-access papers (continued):
Sharing a sentence is not in itself a finding about the gene and the disease.
breast carcinoma (continued). "We recently reported that in spite of their failure to express the tumor suppressor and clock gene Per2, our tissue-isolated human breast cancer xenografts exhibit daily oscillations in the expression of Clock, Cry1 and Bmal1 that were disrupted in the absence of a circadian melatonin signal." (PMID 25099274, 2014). "Interestingly, the previous study reported that knocked-out BMAL1 promotes metastasis in MDA-MB-231 cells, and previously our results showed that BMAL1 was reduced by tumor hypoxia-induced acidosis and recovered by selectively targeting the acidic pH in breast cancer cells." (PMID 32316196, 2020). "Western blot analysis revealed that in both MCF7 and SKBR3 breast cancer cell lines, the protein expression levels of ALDH3A1 exhibited a negative correlation with BMAL1 expression status." (PMID 41228459, 2025). "Rhythmicity of Bmal1 and Per2 promoters in MDA-MB-231 breast cancer cells after serum synchronization could not be observed." (PMID 38199564, 2024). "However, in breast cancer cells, both overexpression of HIF-1α and hypoxia-mimetic agent CoCl2 did not affect the BMAL1 protein expression." (PMID 32316196, 2020). "However, few studies have examined the expression of positive clock factors (BMAL1 and CLOCK) in human breast cancer, largely due to the lack of reliable antibodies." (PMID 30348208, 2018).
glioma (45 papers, 2013 to 2026). A benign or malignant brain and spinal cord tumor that arises from glial cells (astrocytes, oligodendrocytes, ependymal cells). "M2 phenotype microglia can promote glioma proliferation and migration by delivering miRNA-7239-3p to glioma cells via exosomes, regulating their tumor-associated protein expression (BMAL1 down-regulation, CLOCK up-regulation) and reducing tumor cell apoptosis." (PMID 37700840, 2023). "NPAS2 is a protein coded by the Npas2 gene that heterodimerizes with BMAL1, and its expression in gliomas was associated with patients having poor outcomes and high mortality." (PMID 34361055, 2021). "Interestingly, another study of in vitro glioma cells demonstrated that IDH1 mutations are associated with lower expression of BMAL1, CLOCK, PER genes, and CRY genes compared to their wildtype counterparts." (PMID 38173841, 2023). "In addition, both increases and decreases in Bmal1 expression are linked with glioma biology." (PMID 40495887, 2025). "For instance, clock genes inhibited apoptosis on a human glioma cell line, whereas treatment with cisplatin caused a dual effect: the upregulation of clock expression, increasing proliferation; and the upregulation of Bmal1 expression, which increases apoptosis." (PMID 37504857, 2023). "ATP7A expression positively correlated with BMAL1 expression in patients with IDH-WT GBM in the Chinese Glioma Genome Atlas (CGGA)." (PMID 41480765, 2026). "In glioblastoma (GBM), CLOCK or BMAL1 can promote tumor growth by regulating glioma cell proliferation and migration through the NFκB pathway and supporting glioma stem-cell function by managing anabolic metabolism." (PMID 39001398, 2024). "In patients with high-grade glioma, analysis of The Cancer Genome Atlas database reveals that BMAL1 is upregulated compared to patients with low-grade glioma." (PMID 39413708, 2024). "In a computational study using TCGA (The Cancer Genome Atlas) glioma data, CRY1, BMAL1, and RORγ were associated with a higher mutation rate and mutation hotspots in EGFR, TTN (Titin), and PTEN (Phosphatase and Tensin Homologue) genes." (PMID 38378853, 2024). "In another study, the CLOCK/BMAL1 complex within glioma stem cells demonstrated its capacity to upregulate the transcription of LGMN." (PMID 38607733, 2024). "It has also been reported that miR-7239-3p upregulated in M2 microglial exosomes is recruited to glioma cells and inhibits Bmal1 expression, thereby promoting the progression of glioma." (PMID 37759870, 2023). "The lactate-IL-1b-Clock/Bmal1 loop positively affected a number of pathways including cell cycle, DNA damage and cytoskeletal organization in glioma." (PMID 37476290, 2023). "In this context, a recent paper has shown that the exposure of glioma cells to M2 microglial EVs enhanced their growth, migration, and invasion capabilities, by affecting the expression of circadian genes, such as Bmal1 and Clock." (PMID 38020906, 2023). "Further investigations revealed that miR-7239-3p, upregulated in M2 microglial EVs, enters glioma cells and is responsible for Bmal1 gene downregulation." (PMID 38020906, 2023). "In glioblastoma, CLOCK and its heterodimeric chaperone BMAL1 behave as tumor-promoting factors, directly modulating the NF-κB pathway, thereby regulating glioma cell migration and proliferation, and maintaining GSC stemness." (PMID 37700840, 2023). "Overall, by increasing the expression of immunosuppressive microglia in the TME, CLOCK and BMAL1 genes can effectively minimize the response of glioma to immunotherapies." (PMID 38173841, 2023). "An analysis on data from The Cancer Genome Atlas (TCGA) database showed an upregulation of BMAL1 in high-grade glioma patients, while BMAL1 was downregulated in patient-derived glioma stem cells (GSC) and impaired their progression." (PMID 36796229, 2023).
glioma (continued). "Our findings provide evidence of a feed-forward lactate-IL-1b-Clock/Bmal1 loop that drives tumor progression by driving aberrant metabolism and inflammation in glioma." (PMID 37476290, 2023). "Correspondingly, inhibition of BMAL1 in vitro using primary glioma cells results in decreased expression of HIF-1α and VEGF." (PMID 38173841, 2023). "Experimental downregulation of CLOCK and BMAL1 in glioma stem cells (GSCs) results in cell cycle arrest and apoptosis, suggesting that this circadian deregulation is crucial to the growth of GSCs." (PMID 38173841, 2023). "Studies have shown that BMAL1 is highly expressed in gliomas, and regulates the expression of Ang2 and VEGF by regulating HIF-1a under hypoxia, to participate in the formation of tumor microvessels and peritumoral edema." (PMID 35874764, 2022). "Rhythm gene BMAL1 (brain and muscle Arnt like 1) is considered to be a tumor-promoting factor in glioma and plays a key role in the proliferation and migration of glioma cells." (PMID 35874764, 2022). "The expression of BMAL1 is involved in glioma biology, both when it is upregulated and downregulated." (PMID 36556190, 2022). "Recent discoveries highlighted a correlation between BMAL1 overexpression and a decrease in glioma invasiveness, through the inhibition of PI3K/AKT/matrix metalloproteinase-2 signaling pathway." (PMID 36556190, 2022). "The higher efficacy of 1A‐116 was observed at low BMAL1 expression in glioblastoma cells and a differential OS was found when applying 1A‐116 at Zeitgeber times 12 (ZT 12) to glioma‐bearing nude mice." (PMID 36066207, 2022). "Our work revealed that miR-7239-3p, which is secreted by M2 microglial exosomes, enters glioma cells by endocytosis, leading to the inhibition of Bmal1 gene expression, and ultimately the promotion of glioma progression." (PMID 33528793, 2021). "In gliomas, BMAL1 expression was significantly and positively correlated with the tumor MVD (R = 0.915, P < 0.001), suggesting that BMAL1 is closely related to angiogenesis in glioma." (PMID 34815366, 2021). "In summary, we found that miR-7239-3p in the glioma microenvironment is recruited to glioma cells by exosomes and inhibits Bmal1 expression." (PMID 33528793, 2021). "According to in vitro experiments, silencing the expression of BMAL1 in primary glioma cells results in a decrease in the expression of VEGF." (PMID 34815366, 2021). "We found that distinctive phenotypes of microglial cells regulate the expression of circadian genes in gliomas: after co-culture with M2 microglia, the expression of BMAL1 protein decreases, while CLOCK expression increases." (PMID 33528793, 2021). "Upregulation in the expression of BMAL1 was reported in the analysis of the TCGA database in high-grade glioma patients." (PMID 34361055, 2021). "Comparison of BMAL1 positive expression between glioma and peritumoral tissues, and between different pathological grades and peritumoral tissues." (PMID 34815366, 2021). "Glioma migration and invasion were also reduced after ectopic expression of BMAL1, leading to downregulation of p-AKT and MMP-9 signaling pathways." (PMID 34361055, 2021). "In gliomas, either upregulation or downregulation of BMAL1 expression has relevant repercussions on their biology." (PMID 34361055, 2021). "BMAL1 is also considered a pro-tumor factor in glioma that promotes the proliferation and migration of glioma cells." (PMID 34815366, 2021). "After treating glioma cells with M2 and unpolarized microglial exosomes, we found that the expression of Bmal1 and miR-7239-3p were significantly different in the two groups." (PMID 33528793, 2021). "Overexpression of BMAL1 in gliomas led to a poorer survival outcome, indicating a potential tumor promoting role." (PMID 32631383, 2020). "Studies on glioma, head and neck squamous cell carcinoma, lung, colorectal and liver cancers demonstrated that PERs, CRYs and BMAL1 are downregulated in tumours and are likely to harbour tumour suppressing qualities." (PMID 31014368, 2019).
glioma (continued). "The invasiveness of these cells was again increased and decreased by Bmal1 knockdown and overexpression, respectively, suggesting that Bmal1 suppresses the invasion of glioma cells." (PMID 23563360, 2013). "Our previous study has shown that BMAL1 plays an important role in glioma stem cells." (PMID 41480765, 2026). "Previous reports link GSC CLOCK/BMAL1 signaling to glioma immunosuppression." (PMID 41480765, 2026). "Our research had elucidated the circadian oscillations of the clock genes in the U87 glioma cells by employing two different computational models and observed that T16 and T8 time points revealed the highest circadian activity for Bmal1 and Per2 genes, respectively." (PMID 40649908, 2025). "Moreover, BMAL1 regulates the stemness and tumorigenesis of gliomas via the Wnt/β-catenin signaling pathway, with its interaction with glioma stem cells significantly impacting glioma initiation and progression." (PMID 40243466, 2025). "Overexpression of Bmal1 in patients with high-grade glioma-mediated suppression of GBM cell growth." (PMID 40495887, 2025). "Using the U251 glioma cell model, we also observed rhythmic transcriptions of the clock genes, including BMAL1, CLOCK, CRY1, and PER1, which adds novel evidence that the biological clock also functions in vitro, suggesting that this cell line is suitable for biological rhythm research." (PMID 38385622, 2024). "Major mutated CRGs in LGG are PER2, BMAL1, CLOCK and BMAL2, which might indicate these genes are most influencial CRGs to glioma development or metastasis." (PMID 39043735, 2024). "Thus, while in one study BMAL1 knockdown was reported to induced cell-cycle arrest and apoptosis, in a different study BMAL1 overexpression reduced glioma invasiveness, rather pointing to BMAL1 as a potential tumour suppressor." (PMID 36796229, 2023). "BMAL1 overexpression was also found to inhibit cell invasion in human glioma cell lines." (PMID 37400829, 2023). "Furthermore, BMAL1 suppresses cell invasion by blocking the PI3K-AKT-MMP-2 pathway, as seen in BMAL1 KO human lung cancer and glioma cell lines." (PMID 38067152, 2023). "In addition, Bmal1 knocked-down glioma cells exhibited a higher tumor growth rate when injected into mice than control glioma cells, reflecting a major tumor phenotype." (PMID 36183836, 2022). "In gliomas, upregulation or downregulation of BMAL1 expression is also significant." (PMID 36556190, 2022). "Interestingly, BMAL1 overexpression in high-grade glioma patients promoted it as a tumor suppressor in GBM cell growth." (PMID 36556190, 2022). "An upregulation in BMAL1 expression was reported in high-grade glioma patients, highlighting that BMAL1 may work as a tumor suppressor." (PMID 36556190, 2022). "In addition to VEGF, BMAL1 was also positively correlated with the expression of ANG2 in glioma in our study." (PMID 34815366, 2021). "Additionally, BMAL1 expression is positively correlated with the microvascular density and peritumoral edema of glioma." (PMID 34815366, 2021). "In summary, we speculated that BMAL1 might be involved in angiogenesis in human glioma cells by regulating VEGF and ANG2 expression via HIF-1a pathway." (PMID 34815366, 2021). "A subtle difference expression pattern was observed in glioma cells that overexpressed BMAL1." (PMID 34815366, 2021). "RORα and RORβ, which modulate the transcription of Bmal1, were observed to be downregulated in gliomas, and this expression profile was prognostic in a cohort of glioma-diagnosed patients suggesting that its function is associated with tumor genesis and progression." (PMID 34361055, 2021).
glioma (continued). "Finally, by establishing a glioma model in nude mice, we found that miR-7239-3p and Bmal1 gene expression were negatively correlated." (PMID 33528793, 2021). "In the present study, BMAL1 expression was positively correlated with the expression of ANG2 and VEGF, and thus we speculated that high BMAL1 expression might be correlated with the microvascular density of glioma and the degree of peritumor brain edema." (PMID 34815366, 2021). "CLOCK and its binding partner, BMAL1, are thought to contribute to glioma proliferation, migration, stemness and metabolic reprogramming and a recent paper proposed that GSCs use BMAL1 and CLOCK to alter these characteristics and gain a physiological advantage." (PMID 32631383, 2020). "The overexpression of BMAL1 in glioma might in turn activate Wnt/β-catenin which can be also activated by PI3K/AKT pathway." (PMID 32195174, 2020). "An inverse relationship between BMAL1 levels and glioma invasiveness was previously reported." (PMID 32195174, 2020). "Similarly, clinic-based and case-control study has shown overexpression of glioma BMAL1 in comparison to normal brain." (PMID 32195174, 2020). "To determine whether Bmal1 exerts this function in cancer cells from other organs, we examined U251 glioma cells." (PMID 23563360, 2013). "In addition to promote the growth of stem cells in glioma, the BMAL1/CLOCK complex could also recruit immunosuppressive microglia to the TME, thereby establishing conditions associated with poorer prognoses." (PMID 38607733, 2024). "To more directly assess the impact of BMAL1 on the expression levels of HIF-1a, ANG2 and VEGF we used primary glioma cells to construct cell models with BMAL1 overexpression and silencing and to determine whether BMAL1 is involved in HIF-1a, ANG2 and VEGF expression in gliomas." (PMID 34815366, 2021). "We verified our hypothesis by analyzing human glioma tissue to determine the correlation between BMAL1 expression and microvessels, and performed MRI (Magnetic Resonance Imaging) to understand the correlation between the expression of the BMAL1 gene and peritumor edema." (PMID 34815366, 2021). "Therefore, identifying miRNAs that can regulate Bmal1 is of great importance for elucidating the molecular mechanism by which M2 microglia promote glioma progression, and to provide a theoretical basis for the development of biologically-targeted therapy for glioma." (PMID 33528793, 2021). "However, our results support the hypothesis that BMAL1 is involved in glioma angiogenesis by regulating the ANG2/VEGF pathway and affects the degree of peritumor brain edema." (PMID 34815366, 2021). "As the expression level of glioma-related genes was found differentially expressed in the comparison between WT, Bmal1-/- and Cry1/2-KO knockout mice, we suggest that clock genes may have a direct or indirect association with expression patterns of these genes." (PMID 31523185, 2019). "Enhanced 1A-116 efficacy was reported at low-level expression of Bmal1 in GBM cells and a differential overall survival was observed when applying 1A-116 at Zeitgeber times 12 (ZT 12) to nude mouse models with gliomas." (PMID 40495887, 2025). "For instance, in a glioma stem cell study, the CLOCK/BMAL1 complex within these cells was found to stimulate tumor angiogenesis within the glioma TME by modulating HIF1α through the transcriptional regulation of OLFML3." (PMID 38607733, 2024). "The BMAL1/CLOCK complex, essential for maintaining circadian rhythm, is fundamentally necessary for the proliferation of glioma stem cells, with its inhibition curtailing their growth." (PMID 38607733, 2024). "While BMAL1 and CLOCK are vital for GSC survival, PER1, PER2, and PER3 are downregulated in high-grade gliomas." (PMID 39413708, 2024). "Building upon prior findings, the CLOCK/BMAL1 complex was observed to induce the expression of TBK1 in endothelial cells by secreting POSTN, thereby facilitating glioma TME angiogenesis." (PMID 38607733, 2024).